ZNF395 (zinc finger protein 395)
Diseases named in the same sentence as ZNF395 in open-access papers (continued):
Sharing a sentence is not in itself a finding about the gene and the disease.
tumor (10 papers, 2005 to 2024). "Being a member of the C2H2-type zinc finger protein family, ZNF395 is a recently identified nuclear-cytoplasmic shuttling transcription factor that contributes to hypoxia associated inflammation, inhibits immune response and facilitates tumor development." (PMID 39724092, 2024). "In a field with multiple microenvironmental changes resulting from continued exposure to potentially carcinogenic agents, a tumor could be initiated when cells gain fitness advantage for uncontrolled cell proliferation and invasion, such as loss of ZNF395." (PMID 39348078, 2024). "According to RNA sequencing, all tumor samples except one (a human papillomavirus (HPV)-positive tumor) showed lower ZNF395 mRNA levels than the matched NTCT." (PMID 39348078, 2024). "Because NTCT showed an average upregulation and tumor samples an average downregulation of ZNF395 mRNA compared to healthy controls, we investigated ZNF395 levels in each of the 21 paired tumor and NTCT samples." (PMID 39348078, 2024). "Here, our genomic and transcriptomic data showed that an increase in ZNF395 mRNA occurs in non-tumor samples but is decreased in HPV-negative SCCOT samples in association with gene loss." (PMID 39348078, 2024). "The distinct expression patten of ZNF395 in the HPV-positive tumor indicates the difference in pathogenesis between HPV-negative and HPV-positive tumors." (PMID 39348078, 2024). "One of the apoptosis-related genes identified in this study is ZNF395 (also known as papilloma virus binding factor (PBF)), located on chromosome 8p and encoding a transcription factor with a tumor suppressive role in several cancers." (PMID 39348078, 2024). "As gain of chromosome 8 and upregulation of ZNF395 is a specific alteration in non-tumor tongue cells of SCCOT patients, we speculate that the prominent changes seen are caused by an etiologic field effect." (PMID 39348078, 2024). "A recent study proposed that ZNF395 is a novel tumor suppressor gene." (PMID 36139015, 2022). "On the other hand, tumor suppressing activities were assigned to ZNF395." (PMID 26229239, 2015). "By enhancing the production of these factors ZNF395 may support hypoxia-induced inflammation and thus contribute to tumor progression." (PMID 26229239, 2015). "On the other hand, ZNF395 was suggested to have tumor suppressor activities which may rely on its repression of proinflammatory factors." (PMID 26229239, 2015). "Compared to healthy controls, Zinc Finger Protein 395 (ZNF395), a pro-apoptotic tumor suppressor located on chromosome 8p, was the only gene showing increased mRNA level in NTCT whereas decreased in SCCOT." (PMID 39348078, 2024). "We revealed TFs whose expression is linked to a large number of tumor-specific enhancers and further characterized selected TFs for each tumor type (e.g., BRCA: GATA3, FOXA1, ESR1, PRAD: HOXC6, DLX1, KIRC: ZNF395) and for specific tumor subgroups." (PMID 27833659, 2016). "There are no reports of ZNF395 being involved in tumor metastasis." (PMID 24599008, 2014).
infection (2 papers, 2017 to 2024). The state of being infected such as from the introduction of a foreign agent such as serum, vaccine, antigenic substance or organism. "Results demonstrated that RNA2.7FA overexpression and ZNF395 protein knock down could rescue the cell death caused by HANΔRNA2.7 infection." (PMID 39724092, 2024). "The functional relevance of the contribution of ZNF395 to the IFNα-mediated control of specific well characterized antiviral ISGs, we have identified here, is supported by several reports correlating reduced ZNF395 expression in patient in the context of an infection with HIV1, CMV, and EBV." (PMID 28316371, 2017). "Further analysis found that transfection or infection of RNA2.7 did not alter ZNF395 mRNA levels." (PMID 39724092, 2024).
benign tumors (1 paper, 2008). "LOXL2 showed more than 3-fold increased expression in three MPNSTs, whereas ZNF395 showed approximately similar expression levels in the MPNSTs and the benign tumors." (PMID 18522746, 2008).
ZNF395 also shares sentences with these, for which no sentence is quoted: neuroblastoma (2 papers); bone cancer (1); cervical cancer (1); colon cancer (1); diabetic retinopathy (1); invasive carcinoma (1); pancreatic cancer (1); prostate tumors (1); Retinopathy (1); vitiligo (1).